RNU6-827P (RNA, U6 small nuclear 827, pseudogene)
Gene: Small nuclear RNA gene on chromosome 2 (78,882,447 to 78,882,552, forward strand). Ensembl gene ENSG00000202423.
Homologues: Orthologues: chimpanzee U6 (100% identical), macaque U6 (96% identical), dog U6 (87% identical), guinea pig U6 (85% identical), pig U6 (84% identical). Paralogues in human: RNU6-116P (88% identical), RNU6-1060P (87% identical), RNU6-15P (87% identical), RNU6-698P (87% identical), RNU6-1042P (86% identical), RNU6-211P (86% identical), RNU6-25P (86% identical), RNU6-33P (86% identical), RNU6-41P (86% identical), RNU6-455P (86% identical), RNU6-46P (86% identical), RNU6-476P (86% identical), and 1288 more.